CD4 (CD4 molecule)
Diseases named in the same sentence as CD4 in open-access papers (continued):
Sharing a sentence is not in itself a finding about the gene and the disease.
cancer (continued). "We analyzed nine cell types in the dataset, namely, B cells Tregs, CD4+ T cells, CD8+ T cells, macrophages, mast cells, NK cells, cancer-associated fibroblasts (CAFs), and DCs." (PMID 37519793, 2023). "In almost all cancers, the KIFscore was significantly positively correlated with T cell CD4+ TH2, the common lymphoid progenitor, and the T cell follicular helper." (PMID 37711200, 2023). "We designed a cancer vaccine that promotes potent, antigen-specific CD4 T cell responses to MCPyV-LT." (PMID 37711623, 2023). "Recently, in the ICIs treatment of cancer, CD4+ T cells also played an important role as a predictive index of therapeutic outcomes." (PMID 37771774, 2023). "At HIV diagnosis and at first cancer presentation, the median CD4+ T cell count was 147 cells/μL (IQR: 70–290 and 266 cells/μL (IQR: 120–540), respectively." (PMID 38201498, 2023). "CD4+ T cells are widely distributed in various cancers and several studies have shown that levels of CD4+ T lymphocytes gradually decreases with HCC progression." (PMID 37309005, 2023). "While all mice eventually succumbed to the cancer, mice receiving either CD4 or CD8 T cells had a lower cancer burden at 3 weeks after transplant when compared to DPT or no treatment controls." (PMID 36961891, 2023). "Unsupervised clustering of the 79 CD4+ T cell types revealed 10 super cell types across different cancer types." (PMID 36049666, 2023). "CD4 T cells containing cytotoxic granules and exhibiting ex vivo cytolytic activity (CD4 CTLs) have been detected in cancer patients." (PMID 37185301, 2023). "In recent years, multiple studies have demonstrated that CD4+ T cells are critical to the response to cancer immunotherapy." (PMID 37063862, 2023). "Considering the role of cancer-associated mucins in modulating immune cell response and TME infiltration, we analyzed the presence of CD8+ and CD4+ T cells, and PD-L1 immunostaining in the ccRCC microenvironment." (PMID 36902242, 2023). "Further evidence supporting the importance of CD4+ T-cells in cancer initiation comes from a recent large atlas study of colonic epithelium." (PMID 37654482, 2023). "There was also a positive correlation between GOLT1B genetic alterations and CD4+ T lymphocytes, especially the Th2 subset, as well as between GOLT1B expression and the estimated infiltration value of cancer-associated fibroblasts." (PMID 38130634, 2023). "We found that stromal cells, such as cancer-associated fibroblasts (CAFs), most immune cells, such as CD8+ T cells, CD4+ T cells, and antigen-presenting cells, were significantly higher in the low-risk group than in the high-risk group." (PMID 36817452, 2023). "Camrelizumab had an acceptable safety profile in 24 participants with HIV, a CD4+ T-cell count of greater than 100 cells/μL, and advanced cancer." (PMID 37062823, 2023). "Our data revealed that DDR1 expression was negatively correlated with M0 macrophages and activated CD4 memory T cells in most cancers." (PMID 37031216, 2023). "Infiltration levels of CD8 T cells, CD4 T cells, macrophages, and cancer-related fibroblasts (CAF) in TME are associated with the prognosis of numerous cancers, such as gastric cancer, melanoma, bladder cancer, lung cancer, and breast cancer." (PMID 37636564, 2023). "BRD4 was significantly correlated with abundance of activated CD8 T-cell (Act_CD8; rho = −0.445, p < 0.001), and effector memeory CD4 T-cell (Tem_CD4; rho = −0.496, p < 0.001) of TILs across human heterogeneous cancers." (PMID 36711038, 2023). "This study reveals how CD4+ T-cell help optimizes human cDC1 function for inducing a CTL response against cancer cells, which provides strong arguments to engage CD4+ T-cell help in cancer immunotherapy." (PMID 36639382, 2023). "Stem-cell-originating cancer cells co-localized with CD4+ T-cells expressing a high frequency of FOXP3+ cells, as well as upregulation of genes associated with exhaustion including Pdcd1, Ctla4, and Havcr2 (TIM3)." (PMID 37654482, 2023).
cancer (continued). "Contrarily, in younger cancer patients, more than 20% of this population presents a CD4 SIPhigh status, which seems to negatively impact the serological response to the SARS-CoV-2 vaccine." (PMID 37334387, 2023). "Among the upregulated CSIRGs, most were expressed in all of the cell types, including malignant cells (Mal), CD4+ T cells, CD8+ T cells, T cells, NK cells, macrophages cells, B cells, cancer-associated fibroblast (CAF) cells, and endothelial cells." (PMID 37026000, 2023). "This pathway is particularly critical in cancer, and selected mRNA cancer vaccines in development incorporate DC-targeting strategies to facilitate CD4/CD8 T cell responses." (PMID 38005953, 2023). "CD4 CTL subsets identified in this study closely resemble the phenotype of CD4 CTLs detected in cancer patients." (PMID 37185301, 2023). "These immune mechanisms are maintained by distinct cell types in which iASPP has complementary functions, namely oncogene transformed cancer cells and CD4+ T cells." (PMID 36746936, 2023). "Other studies have also defined the function of CD4 T lymphocytes as a “double-edged immunological sword,” since they play a key role in initiating and maintaining the anti-cancer immune response." (PMID 37877827, 2023). "Cancer cells treated with Amy-F showed a considerable reduction in the CD4, CD80 expression, whereas, induced elevation in CD8 and NKG2D expression was observed in Amy-F treated BCCs when compared to the RT group." (PMID 37210478, 2023). "Much of the previous studies have put the focus of research on CD8 T cell instead of CD4 T cell function in cancer." (PMID 37063862, 2023). "Yet, the importance of CD4+ T cells in cancer elimination via secretion of effector cytokines such as interferon-γ (IFNγ) and tumor necrosis factor-α (TNFα) has also been reported." (PMID 39086686, 2023). "In cancer patients, we observed an elevation of senescent T-cells compared to healthy donors (p=0.38 and p=0.004, for CD4 and CD8 respectively)." (PMID 37334387, 2023). "Persistent exposure to cancer antigens induces CD4 T cell exhaustion by upregulating the expression of several co-inhibitory markers, including PD-1, CTLA-4, TIM-3, and Lag-3, and downregulating the production of cytokines such as IFN-γ18." (PMID 37147330, 2023). "There is growing evidence for a cytotoxic subset of CD4+ T cells capable of directly killing cancer cells." (PMID 37190281, 2023). "We find the signature of “helped/licensed” cDC1 in the TME of a large range of human cancers, which argues that CD4+ T-cell help for the CTL response can take place within T cell-infiltrated tumors." (PMID 36639382, 2023). "Recent studies have highlighted a subset of CD4+ T cells expressing cytotoxic markers, such as granzyme B (GrzmB), in human cancers." (PMID 36512410, 2023). "The expression levels of immunosuppressive markers in CD4+ T cells increased with increasing CD4+ T cell infiltration into cancer mucosa." (PMID 37153541, 2023). "IKBIP has a significant relationship with the infiltration of B cells, CD8+ T cells, CD4+ T cells, macrophages, neutrophils, and dendritic cells (DC) across a wide range of cancers." (PMID 36999060, 2023). "During the early phases of cancer, activated immune cells (NKs, CD8+, CD4+ T cells) secrete IFNγ, thereby modulating the activity of macrophages, DCs, Th1 CD4+helper T cells, and B cells to eliminate cancer cells." (PMID 37190141, 2023). "By coordinating mediated immunity cells against cancer cells, Th1 among various subsets of CD4+ T cells serve a direct antitumor role." (PMID 37605131, 2023). "The role of immunosurveillance activities of CD4+ T cells is best characterized in viral-dependent cancer models." (PMID 37623879, 2023). "In conclusion, our study provides fundamental evidence showing that levels of circulating sPD-L1 are significantly positively correlated with the apoptosis of peripheral CD4+T cells in patients with cancer." (PMID 37266424, 2023).
cancer (continued). "The three PIMs with CD82 were upregulated specifically in Th17 cells when compared with naive, T follicular helper (Tfh), Treg, and exhausted cytotoxic T cells within the CD4+ fraction of patients with cancer." (PMID 38039135, 2023). "Nonetheless, the steady and slow reduction of CD4 + T cells in HIV infections correlates with an increased prevalence of HPV infections and HPV-associated cancers." (PMID 37670247, 2023). "In myeloid cells, the top 50 pan-cancer central genes included seven genes involved in myeloid cell differentiation (CD4, FCER1G, IRF8, TYROBP, TLR2, TREM2 and ITGAM), but only two of them (FCER1G and TYROBP) were found among the top 50 DEGs." (PMID 36350625, 2023). "Long overall survival solid cancer patients showed substantially higher levels of CD4+ memory, resting mast cells, T regulatory (Treg) cells and activated NK cells." (PMID 36649303, 2023). "RelB expression was significantly linked with the relative abundance of CD4 T cells, CD8 T cells, B cells, neutrophils, macrophages and dendritic cells in most cancer types." (PMID 37388242, 2023). "Acting as potent antigen-presenting cells (APC), CD40 ligand-activated B cells induce antigen-specific CD8+ CTL cell and CD4+ T cell reactions against cancer cells." (PMID 36765877, 2023). "The results revealed that DDR1 was negatively correlated with the infiltration levels of M0 macrophages and activated CD4 T memory cells, while positively correlated with those of activated dendritic cells in TCGA pan-cancer datasets." (PMID 37031216, 2023). "Other cells types such as activated CD4+CD25-T cells have also shown transient expression of FOXP3 without suppressive capabilities as well FOXP3 has also been described in certain cancers." (PMID 38077395, 2023). "Consistent with early studies in the same aged population, males were more possible to have an imbalanced ratio of CD4+/ CD8+ T cells than females in cancer patients." (PMID 38102684, 2023). "Elevated Tim-3 levels on both TIL CD4 + T cells and TIL CD8 + T cells are associated with higher stages of cancer." (PMID 37567938, 2023). "With direct subcutaneous administration in mice, colon (CT26) and lung (LL2) cancer cells were able to elicit CD4+ and CD8+ T cell-dependent protective immunity." (PMID 37872173, 2023). "Induction of Th1 helper CD4+ T cell immunity is critical for immunomodulation-mediated cancer eradication." (PMID 36875137, 2023). "In contrast, HSP90 inhibition ameliorated CD4+ T cell‐mediated graft versus host disease, a phenomenon on the other side of the coin to cancer immunotherapy." (PMID 36200687, 2023). "With the continuous stimulation of UV, in order to cope with the occurrence of other malignant diseases such as cSCC, LECs need to present antigens to CD4+T cells and regulate the immune response to kill cancer cells." (PMID 37974224, 2023). "CD4+ T cells have complex immunoregulatory functions, with different subtypes exerting opposing effects on cancer progression." (PMID 37744350, 2023). "And G6PD expression is increased in the infiltration levels of B cells, CD8+ T cells, CD4+ T cells, macrophages, neutrophils, and dendritic cells in many cancers, especially in KIRC, LGG, and LIHC." (PMID 37601657, 2023). "What is more, CD4+ T cells can be split into four lineages, encompassing Th1, Th2, Th17 and Tregs, that have an ambivalent role in cancer." (PMID 38067231, 2023). "Cancer patients are characterized by weaker SARS-CoV-2-induced CD4+ and CD8+ T cell responses, compared to healthy individuals." (PMID 36839516, 2023). "As we known, the NKG7 gene was critical for controlling cancer initiation, growth, and metastasis upregulated in the responder, Similarly, upregulated in NK cells and CD4 T cells at the single cell resolution." (PMID 37152010, 2023). "The role of CD4+:CD8+ T cell ratios in cancer is controversial, varying across different cancer types." (PMID 37628721, 2023).
cancer (continued). "IL-4 belongs to the interleukin family and interleukins are small molecular proteins secreted mainly by CD3 + and CD4 + T lymphocytes, which mediate the necessary interactions for the progress of cancer cells." (PMID 37007080, 2023). "Because of expanding knowledge on different T helper subsets and their functions in cancer biology, it is becoming increasingly clear that CD4+ T cells play a vital role in the complex interplay between the immune system and cancer." (PMID 36980536, 2023). "It was concluded that many immune cells aggregated in the H-R cohort, including myeloid dendritic cells, T cell CD8+, and neutrophil in TIMER, cancer-linked fibroblast and macrophage in MCPCOUNTER, T cell CD4+ Th2 and Monocyte in XCELL (all P < 0.05)." (PMID 38071230, 2023). "The primed CD8 and CD4 T cells can directly target and kill cancer cells, and one of the components of the cancer immune cycle is the interference between these T lymphocytes." (PMID 38186570, 2023). "In the TME, overexpressed CD47 on cancer cells bind to SIRPα on myeloid cells, especially macrophages, monocytes, granulocytes, and CD4+ DCs, limiting phagocytosis and intracellular degradation." (PMID 38008741, 2023). "In fact, CD4+ T cells can kill cancer cells through cytokines and chemokines they produced even in the absence of CD8+ T cells and NK cells." (PMID 36766849, 2023). "We analyzed infectivity, replication, cytotoxicity, CD107α upregulation of CD8+ and CD4+ T cells, CD274 (PD-L1) blockade of cancer cells by virus-encoded anti-PD-L1 scFv, and the release of growth factors and cytokines." (PMID 37762490, 2023). "The decrease in Tn, a newly formed reserve cell, suggests that the immune system’s reserves of CD4+T cells are depleted after prolonged activation by cancer antigens." (PMID 36925914, 2023). "CD8+ T cells and CD4+ naive T cells were negatively correlated with TS, while M0 and M2 macrophages were positively correlated with TS in many cancer types." (PMID 36721217, 2023). "The relationship between progressive CD4+ function suppression and cancer development is coherent with cART benefits in the prevention of opportunistic cancers through the restoration of the adaptive immune response." (PMID 37190220, 2023). "MHC II is responsible for antigen presentation to CD4+ T cells, which have recently gained recognition supporting the activation of cytotoxic T cells and mediating checkpoint inhibition response in cancer." (PMID 36901727, 2023). "To further complicate the problem, we have to consider the effect of HSP90 inhibition on T cells, including CD8+ and CD4+ cells, which pivotal effector and essential helper cells in cancer immunotherapy, respectively." (PMID 36200687, 2023). "Further, in epithelioid MMs, a CD4+/CD8+ ratio >1 and a high frequency of CD4+ T cells were associated with an improved survival, consistent with CD4+ T lymphocytes’ role in the stimulation of CD8+ TILS and B-cells against cancer cells." (PMID 36776840, 2023). "We demonstrated that high expression of XCL2 correlated strongly and positively with M1 macrophages and CD8 T cells in pan-cancer, whereas other cells (e.g., macrophage type M0, macrophage type M2, and CD4 T cells) showed inconsistent correlations." (PMID 37905956, 2023). "In initiating and maintaining immune response against cancer, CD4 + T lymphocytes play a crucial role." (PMID 37559025, 2023). "Our present study reveals a significant association between DHX9 expression levels and the infiltration of various immune cells in different cancers, including CD4+ T cells, CD8+ T cells, neutrophils, B cells, DCs and macrophages." (PMID 37214432, 2023). "CD4 T cells are essential for orchestrating anti-cancer immunity in the TME by promoting the killing effect of CD8 cytotoxic T cells." (PMID 37147330, 2023). "Collectively, these results emphasize the significant role of activated CD4+ T memory cells in the prognosis of different cancer types." (PMID 37781029, 2023).
cancer (continued). "Infiltration of macrophages, M2 macrophages, and Th2 CD4+ T cells contributes to cancer immune escape." (PMID 37370814, 2023). "Various immunosuppressive cells are known to dampen antitumor immunity, among which CD4+ regulatory T (Treg) cells are one of the hurdles for immune surveillance against cancer." (PMID 37152373, 2023). "The study found that in cancer tissues, the weak expression rate of CD4 was 46.8% (29 out of 60), while the moderate expression rate was 32.3% (20 out of 62), and the high expression rate was 21% (13 out of 62)." (PMID 37881431, 2023). "The goal is to stimulate the immune system to recognize the neoantigens so that CD8+ and CD4+ T cells are activated to recognize and to destroy the cancer cells." (PMID 36845151, 2023). "This indicated that MTA2 has a substantial association with T cells CD4 in pan-cancer and that MTA2 expression plays an indispensable role in the immune function of pan-cancer." (PMID 37371463, 2023). "BGN has a significant negative correlation with B cells and a positive correlation with dendritic cells, CD8 + T and CD4 + T, macrophages, and neutrophils in various types of cancers including GC." (PMID 37361568, 2023). "The relative abundance of plasma cells, B cells, CD8 T cells, CD4 T cells, T regulatory cells, γδ T cells and natural killer cells, decreased from normal tissue to carcinoma." (PMID 36442992, 2023). "A key finding from this study is the essential role of CD4 T cells in establishing and maintaining an anti-cancer immune response." (PMID 36385142, 2022). "Polyfunctional CD4+ T cells with the ability to produce multiple Th1-type cytokines exhibit many desirable features for cancer immunotherapy." (PMID 35874660, 2022). "Positive correlations were detected among peripheral PD1+CD4+T lymphocytes and each of cancer tissue PD1+CD4+, PD1+CD8+and CD39+CD8+T cells, and among peripheral and cancer tissue CD39+CD4+and CD39+CD8+ T cells." (PMID 35051220, 2022). "Considering that cluster 2 had higher immune-score and a significantly higher abundance of CD8 T cells and activated memory CD4 T cells, which were important immune cells for targeting cancer in immunotherapy, we assigned cluster 2 as hot tumors." (PMID 35677557, 2022). "Several studies support the belief that CD4+ T cells play a critical role in cancer immunity and immunotherapy." (PMID 36139357, 2022). "It is well known that CD4+ T cell, macrophage, neutrophil and dendritic cell play antitumor roles in cancers." (PMID 35907786, 2022). "The gene set positively correlated with EIF4A1 was strongly associated with reduced infiltration of anti-cancer immune cells such as NKT/NK cells and CD4+ T cells, and this accompanied a reduced infiltration score." (PMID 36101357, 2022). "The PD-1/PD-L1 pathway has been shown to be increased in aged dendritic cell subtypes and T cells and CD4+ T cells with features of cellular senescence and increases further with age in many cancers." (PMID 35968783, 2022). "Cytotoxic CD8+ T cells are considered to play a major role in granule-mediated killing of cancer cells, while a greater focus has been put on CD4+ T cells as well as Mtb-infected macrophages to understand immune control in TB." (PMID 36591229, 2022). "A decrease in cancer growth and invasiveness was associated with reduced angiogenesis and also enhanced infiltration of dendritic cells (CD11c+ and MHC-II+) and CD4+ and CD8+ T lymphocytes." (PMID 34533648, 2022). "Recognizing the important role of CD4+ T cells in mediating cancer immunity and understanding the biology of cytotoxic CD4+ T cells will lead to novel approaches to further enhance their direct antitumor activity in patients." (PMID 35928827, 2022). "Despite the detection of responding CD4 T cells, there is some evidence that the cancer patients showed a lower response rate to this peptide (4/11) than healthy donors (15/17) suggesting these responses have been switched to a regulatory phenotype." (PMID 35464453, 2022).